RIN3 (Ras and Rab interactor 3)
Description:
Ras effector protein that functions as a guanine nucleotide exchange (GEF) for RAB5B and RAB31, by exchanging bound GDP for free GTP. Required for normal RAB31 function.
Synonyms: FLJ22439
Tractability: PROTAC: its protein half-life has been measured.
Gene: Protein-coding gene on chromosome 14 (92,513,615 to 92,688,994, forward strand). Ensembl gene ENSG00000100599.
Subcellular location: Cytoplasm; Cytoplasmic vesicle; Early endosome
Pathways (Reactome):
Vesicle-mediated transport: RAB GEFs exchange GTP for GDP on RABs
Gene Ontology:
Molecular function: guanyl-nucleotide exchange factor activity; protein binding; small GTPase binding
Biological process: negative regulation of mast cell chemotaxis; negative regulation of receptor internalization; regulation of vesicle size; endocytosis; signal transduction; vesicle-mediated transport
Cellular component: cytoplasm; cytoplasmic vesicle; early endosome; endocytic vesicle; vesicle; axon; cytosol; dendrite; neuronal cell body
Genetic constraint (gnomAD): Loss-of-function variants: 45 observed, 66.85 expected, observed/expected ratio (o/e) 0.67, 90% interval 0.53 to 0.86. The upper end of that interval is the gene's LOEUF score, 0.86, which puts it in group 3 of 6, group 1 being the genes least tolerant of losing a copy. Missense variants: 1,045 observed, 1,157.3 expected, observed/expected ratio (o/e) 0.9, 90% interval 0.86 to 0.95. Synonymous variants: 479 observed, 486.2 expected, observed/expected ratio (o/e) 0.99, 90% interval 0.91 to 1.06.
Homologues: Orthologues: chimpanzee RIN3 (98% identical), macaque RIN3 (96% identical), pig RIN3 (77% identical), rat Rin3 (77% identical), dog RIN3 (77% identical), mouse Rin3 (77% identical), rabbit RIN3 (68% identical), tropical clawed frog rin3 (48% identical), zebrafish rin3 (42% identical), Drosophila melanogaster spri (22% identical), Caenorhabditis elegans rin-1 (21% identical), Drosophila melanogaster Rabex-5 (7% identical), and 1 more. Paralogues in human: RIN2 (29% identical), RIN1 (22% identical), RINL (15% identical), GAPVD1 (15% identical), VPS9D1 (11% identical), RABGEF1 (9% identical).
Diseases named in the same sentence as RIN3 in open-access papers:
RIN3 is named in the same sentence as 37 diseases in open-access papers, as found by Europe PMC text mining. Sharing a sentence is not in itself a finding about the gene and the disease. The quoted sentences say what the papers report.
Alzheimer disease (14 papers, 2017 to 2024). A progressive, neurodegenerative disease characterized by loss of function and death of nerve cells in several areas of the brain leading to loss of cognitive function such as memory and language. "Genome-wide association studies have identified BIN1 (Bridging integrator 1) and RIN3 (Ras and Rab interactor 3) as genetic risk factors for late-onset Alzheimer’s disease (LOAD)." (PMID 35241726, 2022). "Recent evidence has suggested that dysfunction of RIN3 is associated with several human diseases such as Paget’s disease of bone, Alzheimer’s disease, chronic pulmonary obstructive disease and obesity." (PMID 35359443, 2022). "A genome-wide association study found that mutation at RIN3 is a novel risk locus for Alzheimer’s Disease due to the dysfunction of endocytic trafficking and had effects on the development of Paget’s Disease of Bone." (PMID 35708873, 2022). "In particular, RIN3 is a guanidine nucleotide exchange factor have been significantly associated with Alzheimer’s disease (AD) pathology via endosomal dysfunction." (PMID 34630024, 2021). "Genetic variants in PICALM, BIN1, CD2AP, and RIN3 are associated with increased risk of Alzheimer’s disease, all dementia, and suggested vascular dementia independent of the strong APOE ε4 allele." (PMID 30830563, 2019). "We genotyped four variants in PICALM, BIN1, CD2AP, and RIN3 previously identified as top hits for Alzheimer’s disease, in two prospective studies of the general population totaling 74,754 individuals." (PMID 30830563, 2019). "Furthermore, this research has postulated the potentiality that augmented manifestation of the wildtype RIN3 or manifestation of the RIN3 variation (W63C) could potentially play a role in the development of Alzheimer’s disease." (PMID 37995081, 2024). "The function of rin3 has been studied with respect to Alzheimer’s disease in humans, however the protein structure is not fully defined." (PMID 39221227, 2024). "Increasing evidence suggests that dysregulation of RIN3 activity may contribute to the pathogenesis of several disease conditions ranging from Paget’s Disease of the Bone (PDB), Alzheimer’s Disease (AD), Chronic Obstructive Pulmonary Disease (COPD) and to obesity." (PMID 35359443, 2022).
Paget's disease of bone (7 papers, 2015 to 2023). "Common genetic variants at the RIN3 locus on chromosome 14q32 predispose to Paget’s disease of bone (PDB) but the mechanisms by which they do so are unknown." (PMID 33725152, 2021). "RIN3 missense mutations have been found to predispose to Paget’s disease of bone." (PMID 32438682, 2020). "A GWAS showed that rs10498635 of RIN3 was associated with Paget's disease of bone." (PMID 28445147, 2017). "Our observations also suggest that the variants that predispose to Paget’s disease of bone in humans probably do so by causing a gain-in-function of RIN3, but further work will need to be performed to define the molecular mechanisms by which Rin3 affects bone cell activity." (PMID 33725152, 2021). "Previous GWASs have identified RIN3 in association with lower limb and total BMD in children, and Paget's disease of bone." (PMID 37096546, 2023).
Paget disease (3 papers, 2014 to 2017). A malignant neoplasm composed of large cells with large nuclei, prominent nucleoli, and abundant pale cytoplasm (Paget cells). "Genome-wide association studies enlarged the number of loci associated with PDB, and further fine-mapping studies, combined with functional analysis, identified OPTN and RIN3 as causal genes for Paget’s disease." (PMID 28255281, 2017). "It seems likely that this association reflects a true relationship with BMD as the same RIN3 signal (as determined by conditional analysis) has previously been associated with an increased risk of Paget's Disease [i.e. rs10498635-C OR: 1.44, 95%-CI (1.29–1.60) P = 3.×10−11]." (PMID 24945404, 2014). "In addition, we report a novel association between RIN3 (previously associated with Paget's disease) and LL-BMD (rs754388: β = 0.13, SE = 0.02, P = 1.4×10−10)." (PMID 24945404, 2014). "Furthermore, we report a novel association between a variant within RIN3 and LL-BMD and note its previous association with risk of Paget's disease." (PMID 24945404, 2014).
breast carcinoma (2 papers, 2020 to 2022). "Epigenetic MR analysis identified four CpG sites, cg03260624 near CDC7 gene, cg10816169 near ZNF318 gene, cg03345232 near RIN3 gene, and cg26312998 near RP11-867G23.13 gene, where genetically predicted epigenetic modifications were associated with an increased breast cancer incidence risk." (PMID 35708873, 2022). "But the relationship of RIN3 and breast cancer has not been previously reported." (PMID 35708873, 2022).
cognitive deficits (2 papers, 2022 to 2024). "The development of cognitive impairment was anticipated to be influenced by an abnormal expression of the RIN3 gene, according to a recent study." (PMID 37995081, 2024). "Additionally, a genome wide methylation study of Mexican Americans with mild cognitive impairment uncovered significant hypo-methylation in RIN3 and three other genes." (PMID 35359443, 2022). "They explored the link between RIN3 gene methylation and early cognitive deficits post-transient ischemic attack (TIA) or mild ischemic stroke (MIS), assessing 84 patients within a week of the event using cognitive scales and comparing their RIN3 methylation status to 28 healthy individuals." (PMID 37995081, 2024).
Obesity (2 papers, 2017 to 2022). Accumulation of substantial excess body fat. "We have now shown that rs8018360 (C/T) of RIN3 was related to obesity, with the minor T allele representing a risk factor for this condition." (PMID 28445147, 2017). "We also identified three genes (CROT, TSC1, RIN3) as new candidate susceptibility loci for obesity as well as three genes (ANKK1, ZNF804B, CSRNP3) and chromosome 17p11.2 as new candidate loci for MetS." (PMID 28445147, 2017). "The remaining three genes (CROT, TSC1, RIN3) have not been previously associated with BMI or obesity." (PMID 28445147, 2017). "In addition, single nucleotide polymorphisms in three genes (CROT, TSC1, RIN3) and at four loci (ANKK1, ZNF804B, CSRNP3, 17p11.2) were implicated as candidate determinants of obesity and metabolic syndrome, respectively." (PMID 28445147, 2017). "Three SNPs [rs7808249 (G/A) of CROT, rs1076160 (A/G) of TSC1, rs8018360 (C/T) of RIN3] were related (P < 0.05 in at least one genetic model) to obesity, although there was no SNP significantly [P < 0.0011 (0.05/44)] associated with this condition." (PMID 28445147, 2017). "We have also identified three obesity-related genes (CROT, TSC1, RIN3) that have not previously been implicated as determinants of BMI or obesity." (PMID 28445147, 2017).
schizophrenia (2 papers, 2020 to 2023). A major psychotic disorder characterized by abnormalities in the perception or expression of reality. "DBNL and RIN3 have been shown to be autoantigenic in neurologic diseases like encephalitis and schizophrenia respectively." (PMID 37244972, 2023). "Both IPO13 and RIN3 showed a general high reactivity among all samples, while PAGE2B reactivity was observed in two schizophrenia subjects and two controls." (PMID 33208725, 2020).
Stroke (2 papers, 2019 to 2023). Sudden impairment of blood flow to a part of the brain due to occlusion or rupture of an artery to the brain. "The MR effects on stroke were estimated using 2 variants in the B4GLANT3 and RIN3 regions, where the genetic association information of the other 2 variants were missed in the stroke outcome datasets." (PMID 37096546, 2023).
tauopathy (2 papers, 2021 to 2022). Neurodegenerative disorders involving deposition of abnormal tau protein isoforms (tau proteins) in neurons and glial cells in the brain. "AD-associated genetic variants CD2AP rs9381563 might affect the mechanisms involved both in brain tauopathy and neurodegeneration, and SLC24A4/RIN3 rs10498633 in brain amyloidosis and tauopathy." (PMID 33419465, 2021).
atherosclerosis (1 paper, 2023). A disease characterized by the build-up of fatty material and calcium deposition in the arterial wall resulting in partial or complete occlusion of the arterial lumen. "We considered the SOST cis variant and B4GALNT3, SERPINA1, and RIN3 trans variants identified above as possible instruments for MR analyses of the effect of lower sclerostin levels on atherosclerosis risk." (PMID 37096546, 2023).
brachydactyly (1 paper, 2021). A disease characterized by the presence of brachydactyly, including syndromic and non-syndromic forms. "The SFPR2 gene has been implicated in syndactyly and brachydactyly in humans but the increased levels of expression seem unlikely to contribute to the phenotype observed in Rin3−/− mice." (PMID 33725152, 2021).
giant cell tumour (1 paper, 2015). "RIN3 protein was also detected in osteoclasts from the curetted specimens obtained surgically from a patient with a giant cell tumour of bone." (PMID 25701875, 2015). "RIN3 protein was also detected in human osteoclasts by immunohistochemistry of bone sections from a patient with giant cell tumour of bone." (PMID 25701875, 2015).
glioblastoma (1 paper, 2012). The most malignant astrocytic tumor (WHO grade IV). "Expression of RIN3 was high in all three mast cell lines examined (LAD2, LUVA, and HMC1.1) with little expression in representative epithelial and glioblastoma cell lines." (PMID 23185384, 2012).
glioma (1 paper, 2025). A benign or malignant brain and spinal cord tumor that arises from glial cells (astrocytes, oligodendrocytes, ependymal cells). "In our in-house cohort, the expression levels of CD274, HMGB2, RAC2, RIN3, and SOD3 were elevated in WHO grade IV gliomas compared to grades II/III." (PMID 40852729, 2025).
lymphoma (1 paper, 2013). A malignant (clonal) proliferation of B- lymphocytes or T- lymphocytes which involves the lymph nodes, bone marrow and/or extranodal sites. "Median expression levels were invariably higher for AURKB, BCAT1, BIRC5, BUB1B, PBK and RACGAP1 and lower for FOSB, MAP3K1 and RIN3 by qPCR in lymphoma versus normal B cell samples in both species." (PMID 24130802, 2013).
mastocytosis (1 paper, 2012). A clonal myeloproliferative neoplasm characterized by the proliferation and accumulation of neoplastic mast cells in one or multiple organs or organ systems. "RIN3 was detected by immunohistochemistry in tissue samples from mastocytosis patients." (PMID 23185384, 2012). "Hence, by facilitating KIT down regulation, RIN3 sensitizes mastocytosis cells to the therapeutic kinase inhibitor imatinib." (PMID 23185384, 2012). "Importantly, RIN3 over-expression sensitized a mastocytosis cell line to treatment with the KIT inhibitor imatinib." (PMID 23185384, 2012). "Finally, we demonstrate that elevated RIN3 levels sensitize mastocytosis cells to treatment with a KIT tyrosine kinase inhibitor, suggesting the value of a two-pronged inhibitor approach for this difficult to treat malignancy." (PMID 23185384, 2012).
Senile plaques (1 paper, 2022). Senile plaques are extracellular deposits of amyloid in the gray matter of the brain. "BIN1 directly interacts with RIN3 to initiate RAB5-mediated endocytosis, which is essential for β-secretase (BACE1)-mediated β-secretase cleavage of β-amyloid precursor protein (APP) to generate Amyloid-β (Aβ), the key component of senile plaques in AD." (PMID 35241726, 2022).
Sepsis (1 paper, 2024). Sepsis is defined as life-threatening organ dysfunction caused by a dysregulated host response to infection. "Since hypomethylation is the suggested mechanism behind the abnormal expression of the RIN3 gene in sepsis-induced ARDS and SARS-CoV-2 is associated with Angiotensin-converting enzyme 2 (ACE2) hypomethylation, we may suggest a new genetic association between SARS-CoV-2 induced sepsis and AD." (PMID 37995081, 2024). "They found about forty-one abnormally expressed genes specific to ARDS or sepsis, and RIN3 was one of the hub genes detected." (PMID 37995081, 2024).
tumor (1 paper, 2015). "RIN3 is a negative regulator of mast cell response to stem cell factor, and may play a suppressive role in tumor invasiveness." (PMID 26039411, 2015). "Of the top 10 survival- genes, only three (MAP6, RIN3, and HIST1H2BI) lacked clear-cut evidence of an oncogenic or tumor suppressor role in the literature." (PMID 26039411, 2015).
RIN3 also shares sentences with these, for which no sentence is quoted: dementia (3 papers); amyotrophic lateral sclerosis (1); chronic obstructive pulmonary disease (1); depression (1); encephalitis (1); epilepsy (1); infection (1); ischemic stroke (1); metabolic syndrome (1); neurodegenerative disease (1); neurologic diseases (1); Parkinson disease (1); pulmonary diseases (1); sickle cell disease (1); spinocerebellar ataxia-2 (1); syndactyly (1); transient ischemic attack (1); vascular dementia (1).